ARID1A (AT-rich interaction domain 1A)
Diseases named in the same sentence as ARID1A in open-access papers (continued):
Sharing a sentence is not in itself a finding about the gene and the disease.
tumor (continued). "Although mutant (MUT)-ARID1A generally promotes tumor progression, it also correlates with immune activation and favorable therapeutic sensitivity." (PMID 36369379, 2023). "Recent mechanistic studies have further demonstrated a crucial role for ARID1A in the regulation of gene expression that drives oncogenesis or tumor suppression." (PMID 36980292, 2023). "ARID1A and PIK3CA mutations are frequently found together in OCCC, and they are synergistic in tumour formation." (PMID 38275587, 2023). "ARID1A is a tumour suppressor, involved in transcription by remodelling chromatin in an ATP-dependent manner and was mutated in approximately 25% gastric cancer patients." (PMID 37568604, 2023). "ARID1A acts predominantly as a tumor suppressor gene in many solid tumors, although its functional role seems to be stage and tumor type dependent." (PMID 36890819, 2023). "Molecular tumor testing revealed pathogenic mutations with low VAF in KRAS, ARID1A, BCORL1, and PRKDC." (PMID 37966258, 2023). "Variants in several genes, including frameshift deletion/insertion in ARID1A observed in the parental tumor tissue, were almost maintained in TG8-PDXs of cases UXE-008 and UXE-009." (PMID 37231035, 2023). "Our results reveal various evidence for the involvement of immune-related pathways in luminal tumors harboring ARID1A and PIK3CA mutations, as well as a unique Tumor-infiltrated immune cells composition." (PMID 38017109, 2023). "Taken together, these results suggest that YAP and the Hippo pathway are involved in ARID1A associated EMT and tumour metastasis." (PMID 37173914, 2023). "For this reason, we examined the literature describing ARID1A alterations in human cancer, highlighting its double role as a tumor suppressor or oncogene in different tumor types and stages and focusing on its current use in cancer therapy." (PMID 36890819, 2023). "This suggests the existence of a regulatory axis, involving TRIM32, USP11 and SDC2, which plays a pivotal role in determining the stability of ARID1A and, consequently, its impact as an oncogene or tumour suppressor." (PMID 38041544, 2023). "The down-regulation of ARID1A, which is a tumor suppressor gene, induces expression of angiogenesis-related genes (particularly VEGF and FGF2) and stimulates angiogenesis independently of ACTB encoding β-actin." (PMID 38017409, 2023). "AT‐rich interaction domain 1A (ARID1A) is an essential subunit of the switch/sucrose non‐fermentable chromatin remodeling complex and is considered to be a tumor suppressor." (PMID 37366273, 2023). "To further understand the effect of the ARID1A/YAP complex on tumour invasion, we transfected the truncated plasmid into MDA-MB-231 cells and conducted wound healing and transwell assays." (PMID 37173914, 2023). "The precise role of ARID1A in cancer is highly variable since ARID1A alterations can have a tumor suppressive or oncogenic role, depending on the tumor type and context." (PMID 36890819, 2023). "ARID1A loss promotes the migration and invasion of HCC cells in vitro and promotes tumour growth in mouse xenografts and diethylnitrosamine-induced mouse models of HCC." (PMID 38275587, 2023).
tumor (continued). "Recent advances in cancer genomics have established ARID1A's role as a crucial tumour suppressor, functioning as both a gatekeeper and caretaker." (PMID 38041544, 2023). "As for ARID1A, the DNA HRR inefficiency caused by PTEN depletion or mutation, sensitizes tumor cells to PARPi, both in vitro and in vivo." (PMID 36910637, 2023). "ARID1A mutations, a common driver event in HCC tumorigenesis, undermine mismatch repair thus leading to a higher TMB and an elevated number of tumor-infiltrating lymphocytes and PD-L1 expression." (PMID 37189643, 2023). "Due to its central role in transcriptional regulation and the maintenance of DNA integrity, ARID1A harbors the potential to be a powerful tumor suppressor." (PMID 37627124, 2023). "ARID1A is frequently mutated in cancers, especially in gynecologic ones, but very little attention has been paid to determine ARID1A levels in tumor specimen." (PMID 37627124, 2023). "ARID1A is a tumor suppressor and represents the most frequently altered gene of the SWI/SNF complex in human cancers." (PMID 37400502, 2023). "Our data argument in favour of a paradigm is that ARID1A affects tumour metastasis by inhibiting the production of the YAP/TEAD complex and regulating the EMT signalling pathway." (PMID 37173914, 2023). "Having identified ARID1A as an interesting C2TSG protein in different tumor entities, what would be the best strategy to obtain suitable mimetic drugs to substitute for the tumor lost ARID1A protein?" (PMID 36139547, 2022). "The tumor malignance progressed over time, showing that the percent of adenocarcinoma further increased in 4-month-old Arid1a-deleted prostates relative to that in 3-month-old mice." (PMID 36435834, 2022). "In the present review, all of the 23 included studies consistently suggest that ARID1A is a tumor suppressor in CRC." (PMID 35421925, 2022). "Consistently, all of the 23 relevant studies report that ARID1A functions as a specific tumor suppressor in CRC." (PMID 35421925, 2022). "ARID1A has been found to affect metastasis and tumor cell proliferation in functional investigations." (PMID 35028302, 2022). "The majority of ARID1A mutations are frameshift or nonsense mutations that occur throughout the coding region, suggesting that ARID1A functions as a tumor suppressor." (PMID 36435834, 2022). "ARID1A dysfunction is associated with impairment of the BAF complex and altered HDAC1/BRD4-driven transcription activities to suppress tumor growth." (PMID 35453496, 2022). "Knockdown of HERVH in the ARID1A KO cells greatly reduced both the number and the size of the observed tumor spheres." (PMID 35715442, 2022). "Numerous studies have identified ARID1A as a bona fide tumor suppressor during the oncogenic process, and its downregulation and mutations have been frequently reported in a broad spectrum of cancers, including gastrointestinal tract tumors." (PMID 35611248, 2022). "Intriguingly, even after excluding hypermutated samples, we find somatic point mutations of important cancer genes including PI3KCA, PTEN and ARID1A to be under-represented in high-CIN bulk tumours and high-CIN cancer cell lines (Figure A7D)." (PMID 35326573, 2022). "Taken together, our data suggest that liquid (blood) biopsies identify ARID1A alterations at a frequency similar to that found in primary tumor material." (PMID 36077815, 2022). "Recent studies have revealed that ARID1A loss impairs the expression of IFN signaling components, especially Th1-type chemokines (CXCL9 and CXCL10), to compromise effector T-cell tumor trafficking and antitumor immunity." (PMID 36435834, 2022).
tumor (continued). "Using combined analysis of chemical tools and proteomics, another tumor suppressor, AT-rich interactive domain-containing protein 1A (ARID1A), has been introduced as an unbiased candidate substrate of HDAC8." (PMID 36231123, 2022). "ARID1A levels were highest in WT prostates, and its expression was negatively correlated with tumor malignancy, with higher expression in PtenPC−/− mice than in PtenPC−/−; Trp53PC−/− mice." (PMID 36435834, 2022). "As a tumor suppressor, ARID1A was already identified in various cancers as being able to modulate cellular proliferation, invasion and metastasis." (PMID 36269546, 2022). "Overall, ARID1A is the most frequently mutated SWI/SNF subunit across cancer types and has a tumor-suppressive function, whereby it triggers cancer development by interfering with the DNA-damage response and cell cycle pathways." (PMID 35409155, 2022). "All these studies indicate that loss of ARID1A is associated with oncogenic cell transformation, which suggests a tumour suppressor role for ARID1A in neoplasms originating from the endometrium." (PMID 35167193, 2022). "Reflected by changes in tumor volumes and histology, we found that Arid1a deleted tumors were largely refractory to ADT as compared to Pten-deleted lesions." (PMID 36435834, 2022). "Here, we show that deletion of Arid1a in Pten-null PCa models promotes tumor progression in conjunction with dramatic remodeling of the TME toward a protumor immune profile." (PMID 36435834, 2022). "However, ARID1A mutational status may be a good predictor of immunotherapy outcomes: ARID1A deficient OC mouse model showed higher mutational burden, more tumor-infiltrating lymphocytes, and elevated levels of programmed cell death-ligand 1 (PD-1), providing an opportunity for immunotherapy." (PMID 36430148, 2022). "The connection between immune infiltrating cells and ARID1A expression was investigated using the tumor Genome Atlas (TCGA) dataset for gene set enrichment analysis (GSEA)." (PMID 35028302, 2022). "Recently, another study identified that miR-185-5p-induced suppression of AT-rich interaction domain 1A (ARID1A), a tumor suppressor gene, was associated with poor prognosis and adverse outcomes." (PMID 36287119, 2022). "The purpose of this review is to discuss how inactivating mutations in AT-rich interaction domain 1A (ARID1A), a component of the chromatin remodeling SWI/SNF complex, affect DNA damage repair in tumor cells." (PMID 36123603, 2022). "ARID1A mutant cases showed significantly higher CD8+ cells and CD68+ cells (tumour‐associated macrophages, TAMs) in the stroma relative to tumour." (PMID 35647895, 2022). "Numerous mutated genes correlated with tumor therapy response, such as EGFR, KRAS, ARID1A, and SMARCA4." (PMID 36290859, 2022). "ARID1A is shown to have a tumor suppressor activity, which is consistent with our observation of an excess of nonsense mutations in it." (PMID 35634240, 2022). "The ARID1A (AT-rich interaction domain 1A), coding for the BAF250a subunit of BAF, is a tumor suppressor gene often mutated in RCC and other types of carcinoma." (PMID 35055428, 2022). "While certain tumor types did have higher rates of ARID1A alterations in the tissue than we found in the blood, others had lower frequencies: breast, ~5% vs. 6.1%; head and neck, ~4.5% vs. 5.3% (tissue versus blood)." (PMID 36077815, 2022). "IHC using anti-ARID1A antibody (clone D2A8U, Roche) showed complete loss of expression on the tumor cells." (PMID 35125107, 2022). "The role of ARID1A as a prognostic marker remains inconclusive since it has been described as both an oncogene and tumor-suppressor gene." (PMID 35205774, 2022).
tumor (continued). "The ARID1A-containing SWI/SNF complex (ARID1A-SWI/SNF) specifically plays an important role in tumor suppression." (PMID 35883668, 2022). "In vitro cell models and genetically engineered mouse models have provided cogent evidence to support the functional role of ARID1A in tumor suppression." (PMID 36123603, 2022). "Previous studies have attributed functional consequences to ARID1A-loss in the context of MYCN-amplified tumours, and some authors have postulated ARID1A as the main driving tumour suppressor in 1p36-lost MYCN-amplified cases." (PMID 36057593, 2022). "Mechanistically, Arid1a promotes tumor initiation by increasing CYP450-mediated oxidative stress, while Arid1a loss after initiation decreased chromatin accessibility and reduced transcription of genes associated with metastasis." (PMID 36435834, 2022). "As a tumor suppressor gene, ARID1A is essential for regulating cell cycle, facilitating DNA damage repair, and controlling expression of genes that are essential for maintaining cellular differentiation and homeostasis in non-transformed cells." (PMID 36123603, 2022). "ARID1A is described as a key tumor suppressor in a broad array of cancers, such as HCC and ovarian carcinoma." (PMID 36435834, 2022). "The genes significantly associated with tumor size were ADAMTS10 (p = 0.004, r = 0.585) and ARID1A (p = 0.004, r = 0.585)." (PMID 35055428, 2022). "Judged by histology quantitation, IHC analysis and immunoprofiling data, NF-κB inhibition compromised Arid1a-deleted tumor progression along with the reduced PMN-MDSC infiltrations and expansion of CD8+ T cells." (PMID 36435834, 2022). "Loss of tumour suppressor genes PTEN and ARID1A, caused by oxidative stress from iron-rich endometriotic cysts have been found in both EAOC tumours and adjacent endometriotic tissue." (PMID 35681688, 2022). "The presence of well-known mutations reported in genes that commonly occur in EAC, known as driver mutations like ARID1A, CDKN2A, KRAS, APC, SMAD4, and PI3KCA, and a high tumor mutation burden (TMB) level makes EAC a highly heterogeneous disease." (PMID 35328735, 2022). "There is evidence that ATR inhibitors are efficient in the treatment of ARID1A- tumor cells, however clinical verification of the concept is still lacking." (PMID 36249060, 2022). "Previous research has revealed the function of ARID1A mutation in impairing mismatch repair (MMR) function, increasing the tumor mutation burden (TMB) and predicting good prognosis to cancer immunotherapy in vivo." (PMID 36229854, 2022). "ARID1A failure has previously been related to tumor growth but has little predictive significance in HCC patients, according to previous study." (PMID 35028302, 2022). "The ARID1A mRNA expression degree between normal tissues and tumor tissues was investigated using TCGA data and a bioinformatics method." (PMID 35028302, 2022). "Somatic AT-rich interaction domain 1A (ARID1A) mutations are present in up to 55% of OCCC tumours, and concomitant activation of the phosphoinositide 3-kinase (PI3K) catalytic subunit promotes tumour growth." (PMID 35406519, 2022). "All of these results point to ARID1A participating in tumor start, particularly in the development of liver tumor." (PMID 35028302, 2022). "Recent studies have revealed that ARID1A loss impairs IFN signaling, especially Th1-type chemokine (CXCL9 and CXCL10) expression, to compromise effector T-cell tumor trafficking and antitumor immunity." (PMID 36435834, 2022). "Recent data suggest that ARID1A participates in tumor progression through its effects on the control of cell cycle, modulation of cellular functions such as epithelial-to-mesenchymal transition, and regulation of various signaling pathways." (PMID 36362284, 2022).
tumor (continued). "While liver-specific deletion of ARID1A in mice conferred resistance to tumor initiation, its deletion in established tumors facilitated tumor progression and metastasis." (PMID 35669430, 2022). "At the molecular level, these tumor characteristic mutations included PTEN (88%), RPL22 (33%), KRAS (35%), PIK3CA (54%), PIK3R1 (40%), and ARID1A (37%) with high TMB levels (18 × 106 Muts/Mb) and certain TIL." (PMID 36578004, 2022). "Considering the close relationship between ARID1A and ARID1B, it would be compelling to investigate their tumor site-specific associations with KRAS pathway in future research." (PMID 36439454, 2022). "For instance, tumor suppressor activity is correlated with reduced ARID1A expression in CRC tissues." (PMID 35402625, 2022). "Patient TOMAS-25 had three deleterious ARID1A indels, while patient TOMAS-26 tumor sample harbored a gain-of-function mutation in the ERBB2 gene, predicted as “possibly damaging” on protein function." (PMID 36110934, 2022). "This indicated that ARID1A functions in an oncogenic capacity during tumor initiation and a tumor suppressor capacity during tumor progression and metastasis." (PMID 35669430, 2022). "The association of ARID1A with survival, MSI (Microsatellite-instability), immune checkpoints, TIL (tumor-infiltrating lymphocyte), and downstream immune pathways were explored and potential mechanisms was given." (PMID 36281289, 2022). "In conclusion, the present study shows for the first time the impact of ATRi on ARID1A mutation in CRC cells, as well as in primary tumor material from CRC patients." (PMID 36249060, 2022). "In CCA tumors, decreased expression of ARID1A was associated with CCA progression and metastasis, indicating the tumor-suppressor function of ARID1A in CCA." (PMID 35070505, 2022). "More importantly, A20 enhancer activation abrogated the difference in tumor growth between mice bearing WT and Arid1a KO cells, and MDSCs, CD8+ T cells and IFNγ+ expressing CD8+ T cells were present in similar proportions." (PMID 36435834, 2022). "The present review highlights ARID1A serving as a potent tumor suppressor and an important prognostic factor in CRC." (PMID 35421925, 2022). "Together, our data suggest that the combination of an OV backbone armed with amiR-4 and the small-molecule inhibitor GSK126 facilitates tumour cell death via a synthetic lethal interaction between ARID1A and EZH2." (PMID 35393414, 2022). "ARID1A tended to have a positive correlation with tumor size and tumor stage while GTF2H2 and PRKRIR tended to have a negative correlation with tumor size and tumor stage." (PMID 35615147, 2022). "Since its discovery as a tumor suppressor, ARID1A has entered center stage as an agent for synthetic lethal drug screening." (PMID 36123603, 2022). "The association of ARID1A with survival, MSI (Microsatellite-instability), immune checkpoints, TIL (tumor-infiltrating lymphocyte), and downstream immune pathways was explored." (PMID 36281289, 2022). "Altogether, we demonstrated that ARID1A biochemically, functionally, and clinically participates in tumor progression and potential treatment strategies across many types of human cancer." (PMID 34671561, 2021). "Excepting for one study indicating the carcinogenic functions for ARID1A, the remaining 28 included studies suggest that ARID1A is a tumor suppressor in CCA." (PMID 34249744, 2021). "They found that ARID1A was highly expressed in ICC tumor tissues, showing a total of 68% (77/113) tumor tissues presented with positive immunohistochemical staining in ICC." (PMID 34249744, 2021).